KRAS (KRas proto-oncogene, GTPase)
Diseases named in the same sentence as KRAS in open-access papers (continued):
Sharing a sentence is not in itself a finding about the gene and the disease.
cancer (continued). "Inhibition of the KRAS activator SOS Ras/Rac guanine nucleotide exchange factor 1 (SOS1) is an effective approach when treating cancers driven by KRAS." (PMID 33801965, 2021). "Core Tip: KRAS mutation is currently listed as an additional prognostic factor in AJCC-UICC staging guidelines, NICE, Australian Cancer Care, and ESMO guidelines on colorectal cancer." (PMID 34940086, 2021). "Although gain-of-function mutations of KRAS and BRAF have been identified as a contributor to SHP099 resistance, more than 77.4% (233/301) of all cancer cell lines with the wild types of both KRAS and BRAF were resistant to SHP099 treatment." (PMID 34790119, 2021). "Among gene alterations involved in cancer development, kirsten rat sarcoma (KRAS) represents the most common oncogene driver in human cancer." (PMID 35004317, 2021). "Because of its high incidence in different tumors and its role in cancer initiation and progression, many efforts have been made in finding effective treatments directly or indirectly targeting KRAS." (PMID 33777798, 2021). "Biologically, the activation of bypass signaling is presumably beneficial for KRAS mutant cancer cells to survive by coping with hypoxia and accelerating metastasis." (PMID 34680229, 2021). "The acute dependency of RAS-driven cancer cells on BER enzymes was made evident from the results of a genome-wide RNAi screen to identify synthetic lethal interactions with the KRAS oncogene." (PMID 34204734, 2021). "Further research will help to identify more detailed mechanism of interplay between these two kinases and their role in biology of KRAS mutant cancer cells." (PMID 34955846, 2021). "TCRA3V and TCRA11V-expressing CD8+ T cells exhibited specific cytotoxicity, irrespective of tissue of origin, against all HLA-A*03:01 or HLA-A*11:01-matched KRAS G12V+ cancer cell lines, respectively." (PMID 34272369, 2021). "In vitro studies of 4-AAQB alone, or in combination have demonstrated significant anti-cancer effects on KRAS mutant CRC cell lines." (PMID 34299137, 2021). "Lung tumors driven by strong cancer drivers (mutant EGFR and Kras) harbored few mutations in cancer-related genes, whereas tumors driven by MYC, a weak driver in the murine lung, harbored recurrent clonal oncogenic KRAS mutations." (PMID 34200786, 2021). "Altogether, these data argue that the increase of KRAS expression observed in KRAS mutant cancers is driven not only by an overall increase in KRAS expression, but by altered splicing favoring an increase in the ratio of KRAS4A to KRAS4B transcripts." (PMID 34257283, 2021). "Given the role of KRAS in cancer, and the propensity of other oncogene promoters to contain G4 structures, this regulatory mechanism involving HMGB1 warrants further investigation." (PMID 34680084, 2021). "KRAS is the most commonly mutated (86%), followed by NRAS (11%), and HRAS (3%) in RAS-driven human cancers." (PMID 34956887, 2021). "The RAF-MEK-ERK signaling network is a driver of KRAS-dependent cancer growth, and ERK inhibition is an effective therapeutic approach for KRAS mutant PDAC." (PMID 34852220, 2021). "Despite KRAS being an important molecule in mostly human cancer, including pancreatic and breast, numerous efforts in years past have persisted in cancer therapy targeting KRAS mutant." (PMID 34830757, 2021). "Although the panRAF inhibitor TAK-632, and the BRAF inhibitors PLX4720 and dabrafenib inhibit BRAF more potently than CCT3833 in in vitro enzyme assays, CCT3833 is more potent at inhibiting KRAS-mutant cancer cell growth, so we examine downstream signaling." (PMID 33130216, 2021). "By targeting tyrosine kinase FAK and laminin subunit LAMB3, miR-1298 inhibits the growth of KRAS-driven cancer cells." (PMID 34503246, 2021). "KRAS is one of the Ras superfamily isoforms (N-RAS, H-RAS, and K-RAS) that frequently mutate in cancer." (PMID 34830757, 2021).
cancer (continued). "Another indirect anti-RAS strategy involves targeting the DNA damage response (DDR) that allows cancer cells to counteract the lethal consequences of oncogenic KRAS-induced replicative stress and genomic instability." (PMID 34852220, 2021). "More importantly, several studies have indicated that reversing adaptive resistance to MEK inhibitors is a more effective application of SHP2 inhibitors in KRAS-dependent cancers." (PMID 34742312, 2021). "The reliance on Gln creates a Gln dependent G1 cell cycle checkpoint, which KRAS mutant cancer cells are able to bypass in states of Gln depletion, instead arresting in S/G2." (PMID 33466360, 2021). "In oncogene mutated cancers like KRASG12D-driven PDAC (Pancreatic Ductal Adenocarcinoma) and MYC/KRAS or MYC/ERBB2-ablated breast cancer, cancer cells predominantly rely on OXPHOS for energy production." (PMID 34557865, 2021). "Although there are limitations, the appearance of LC-2 degrader creates new opportunities for targeting KRAS mutants in cancer treatment, which is of great significance." (PMID 34249939, 2021). "This work points also to RAS dimerization as the basis for wild-type KRAS’s inhibitory effect on mutant KRAS-driven cancers and also as the basis for MEK inhibitor sensitivity." (PMID 34680951, 2021). "Single mutation or concomitant mutations in both KRAS and BRAF genes have been identified in different type of cancers." (PMID 34578339, 2021). "KRAS inhibitors are in phase I clinical trials, and some early data have showed inactivity of some cancer cells after treatment, while others avoid this effect to restore proliferation." (PMID 34257597, 2021). "The increase in viability of KRAS-ablated cancer cells relative to precancerous cells was therefore considered to be due to various degrees of KRAS dependence for survival." (PMID 33674596, 2021). "In cancers, Gal-3 is associated with RAS signaling, and thanks to its carbohydrate recognition domain, Gal-3 can interact with KRAS-GTP, stabilizing it in its active state." (PMID 34112916, 2021). "Major pathways, such as the RAF/MEK/ERK and PI3K/AKT/mTOR networks, are regulated by activated KRAS for the progression of cancer survival." (PMID 33830081, 2021). "A combination therapy of the ATRi ceralasertib and radiation decreased the number of tumour-infiltrating Tregs in mouse models of KRAS-mutant cancer, as well as in a mouse model of hepatocellular carcinoma." (PMID 34885119, 2021). "Comparing the mutation status of cancer critical genes in PUMC-CRC1 with that in 19 commonly-used CRC cell lines, it was proved that PUMC-CRC1 with APC (p.T1493fs), KRAS (p.G12V) and SMAD4 (p.V506A) mutations was a unique MSS CRC cell line." (PMID 34162944, 2021). "p62/SQSTM1 deficiency in cancer cells significantly impedes cancer cell growth and inhibition of p62/SQSTM1 suppresses KRAS-driven lung cancers in a genetically engineered mouse model." (PMID 33802014, 2021). "A different approach taken more recently is to study how mutant KRAS alters different cancer hallmarks, including evasion of the immune system and dysregulation of cellular energetics." (PMID 34200676, 2021). "This value of VAF represents the LOD for KRAS variants in our cohort and is in the range of analytical sensitivity reported in other studies for targeted NGS assays to evaluate cfDNA in cancer patients." (PMID 34640513, 2021). "Considering the immunosuppressive microenvironment characterizing KRAS mutant cancers, results from clinical trials utilizing this mechanism are anxiously awaited." (PMID 33777798, 2021). "This suggests that KRAS can promote cancer resistance to ferroptosis by signaling through NRF2 to upregulate system xc−." (PMID 34830482, 2021).
cancer (continued). "The three RAS genes (HRAS, NRAS and KRAS), hereafter collectively referred to as oncogenic RAS, are the most frequently mutated driver proto-oncogenes in cancer, with KRAS being the most prevalent." (PMID 34485382, 2021). "Our dynamical analysis suggests that the downregulation of KRAS, mTOR and autophagy are crucial in anti-cancer therapy." (PMID 33925206, 2021). "Here, a therapeutic strategy is described for KRAS G12C mutant cancers by the combination of KRAS G12C and FAK inhibition." (PMID 34151545, 2021). "Several previous reports have shown that targeting KRAS mutant cancers relies on the identification of unique targets." (PMID 34003553, 2021). "Unfortunately, all the attempts made until now have been unsuccessful, driving the necessity to explore alternative strategies for targeting KRAS-driven cancer." (PMID 32948832, 2021). "RAS mutations are the most commonly found oncogenic alteration in human cancers, most frequently observed in KRAS (85%), and to a lesser degree in NRAS (12%) and HRAS (3%)." (PMID 34919052, 2021). "In KRAS mutant cancer cells, only inhibition of both the PI3K/AKT and MEK pathways resulted in complete inactivation of mTOR and increased cell death." (PMID 34830951, 2021). "Dual inhibition of CHK1 and the GLUT1 glucose transporter is synergistically cytotoxic in KRAS mutant cancer cells." (PMID 34852220, 2021). "As a result, perturbations of stress‐adaptive mechanisms that enable cancer cells to grow and survive under adverse conditions constitute a promising strategy to target KRAS‐mutant cancer." (PMID 34369083, 2021). "Both mTOR and autophagy are upregulated in KRAS mutant cancer cells; therefore, chloroquine has been used for treating cancer in the clinic." (PMID 33925206, 2021). "The recent development of highly specific irreversible inhibitors for KRAS G12C holds promise for the treatment of LUAD and other cancer forms with this type of KRAS mutation." (PMID 34330898, 2021). "Taken together, our data support the further clinical evaluation of CCT3833 in patients with KRAS-mutant cancers." (PMID 33130216, 2021). "The precise mechanism of resistance in patients with cancer treated with KRAS G12C inhibitor is unclear at the moment." (PMID 34064232, 2021). "Oncogenic KRAS activation has been shown to rewire the metabolic program of cancer cells to fuel the energetic and biosynthetic demands of deregulated proliferation, leading to elevated production of intracellular ROS." (PMID 34369083, 2021). "A deeper understanding of the cancer biology and immune system interactions that fuel carcinogenesis in KRAS mutant tumors is essential for developing new drugs and improving disease prognosis." (PMID 35096591, 2021). "The prognostic value of KRAS and HRAS expression has been evaluated in various types of cancers so far, but only few studies indicated the association between the RAS family overexpression or mutation and the high degree lesions." (PMID 33549031, 2021). "Inhibitors of KRAS effector signaling networks are the most promising indirect strategy to target mutant KRAS function for cancer treatment." (PMID 34852220, 2021). "Loss of the transcription factor Wilms tumor 1 (WT1) has been correlated with decreased proliferation and increased cell senescence in KRAS driven cancer cell lines." (PMID 33777798, 2021). "AURKA inhibitors and CDK inhibitors both have shown promise in the treatment of various types of cancer, including KRAS-mutant cancers." (PMID 34607583, 2021).
cancer (continued). "Core cancer signaling pathways mediated by KRAS, TNF-alpha and JAK/STAT proteins were also found near the very top of the list." (PMID 34368836, 2021). "Concurrent pharmacologic targets of the RAF/MEK/ERK and PI3K/AKT/mTOR pathways have been reported in KRAS-driven cancer models, but clinically this strategy has been limited by additive toxicity." (PMID 35095481, 2021). "This Ras-isoform dependent propensity to promote stemness strikingly correlates with the mutation frequency of RAS genes, with KRAS, NRAS and HRAS being mutated in 75%, 17% and 7% of RAS-mutant human cancers." (PMID 33544116, 2021). "Based on that, the ERN1-JNK-JUN pathway holds significance in terms of sensitizing the KRAS-driven cancer cells to MEK inhibitors." (PMID 34781949, 2021). "Our work supports a novel Hsp90 drug development and treatment rationale in multiple KRAS-driven cancer types." (PMID 33672199, 2021). "Although KRAS serves as regulation of cellular process, abnormal mutated and GTP-bound KRAS is highly expressed in human cancers." (PMID 34830757, 2021). "KRAS mutant driven cancer cell lines exhibit synthetic lethal vulnerability towards pyrimidine biosynthesis." (PMID 34123854, 2021). "To determine the downstream effector of circCD44-miR-502–5p, we scanned the target genes of miR-502–5p using the online tool TargetScan and found that KRAS was one of the most vital genes involved in the tumorigenesis and progression of many cancers." (PMID 34696797, 2021). "A novel approach to developing treatments for KRAS mutant cancers, such as those targeting synthetic lethality and metabolism, is expected in the future." (PMID 33562094, 2021). "Numerous studies have shown that the inhibition of mutant KRAS activity in PC can effectively control tumor growth resulting in cancer cell death." (PMID 33692690, 2021). "Adaptive resistance is especially important in BRAF and KRAS mutant cancers, that demonstrate reactivation of the MAPK signaling pathway." (PMID 34071428, 2021). "Given this critical role of glutaminolysis and NRF2/oxidative pathway, it has become an exciting therapeutic target to combat KRAS driven cancers." (PMID 34944853, 2021). "Another inhibitor of the SOS1-KRAS interaction is BAY-293, which has demonstrated efficacy in KRAS-driven cancers in preclinical studies." (PMID 35083149, 2021). "To this end, we compared the effects of CRISPR/Cas9-mediated KRAS knockout in premalignant and cancer-derived PDAC cell lines." (PMID 33674596, 2021). "The results demonstrate that KEAP1 mutations activate the NRF2 antioxidant program and promote LUAD progression in concert with mutant KRAS, demonstrating that cancer cells can overcome oxidative stress barriers during tumorigenesis." (PMID 35070984, 2021). "We also explore unique signaling, TME and stromal targeting via novel small molecule inhibitors, which target KRAS, FAK, CCR2/CCR5, CXCR4, PARP and cancer-associated fibroblasts." (PMID 34771675, 2021). "Although there have been molecules identified to have such potential in treatment of KRAS-driven cancers, a substantial amount of effort is still needed to establish treatment strategies based on these discoveries." (PMID 34781949, 2021). "This points that KRAS‐mediated regulation of AATs is crucial for the uptake of AAs, mTOR activation, and cancer cell proliferation." (PMID 34003553, 2021). "In sum, we have discovered a distinct KRAS signaling axis with actionable therapeutic potential for the treatment of KRAS-mutant cancers." (PMID 34504076, 2021). "For example, activating mutations in KRAS/NRAS are frequently accompanied by loss of function of CDKN2A/B in melanoma, lung, pancreatic, and other cancers." (PMID 33769711, 2021).
cancer (continued). "In Colo357, A-549, and Calu-1 human cancer cell lines, KRAS prenylation was found to be inhibited by FTI-277 and GGTI-298 co-treatment." (PMID 33917906, 2021). "In the setting of PDAC and other cancers, the molecular mechanisms by which KRAS functions at the cell membrane to activate its effectors are of intense interest and translational importance for drug discovery that remain incompletely understood." (PMID 34680275, 2021). "Cancer driver genes as BRAF and KRAS are usually found mutated in serrated polyps, along with MSI and CIMP (CpG island methylator phenotype)." (PMID 33672345, 2021). "Ferroptotic cancer cells release oncogenic KRAS protein which drives macrophages to enrich and switch to an M2-like pro-tumoral phenotype via STAT-dependent fatty acid oxidation." (PMID 34496935, 2021). "One study involved the knockdown of MAPK and autophagy genes in various iterations in KRAS mutant cancer cell lines." (PMID 34830283, 2021). "The induction of sonic hedgehog (SHH) by KRAS in cancer cells triggers the expression of the transcription factor GLI1 in fibroblasts." (PMID 33691728, 2021). "Much of this discrepancy is probably attributed to co-existing cancer-specific genetic or epigenetic aberrations of each cancer type, which can form different genetic and signaling networks with oncogenic KRAS." (PMID 34771644, 2021). "There are currently five active clinical trials that involve the combined inhibition of the RAS/MAPK pathway and autophagy for patients with KRAS mutant cancer." (PMID 34830283, 2021). "The results have supported the view that inactivation of mutant KRAS is critically important for successful cancer treatment, in accordance with the oncogene addiction concept." (PMID 33674596, 2021). "Next-generation sequencing analysis of 50 cancer-related gene mutations, including driver genes in PDAC, found that the combination of KRAS and SMAD4 mutations is an independent adverse prognostic factor in PDAC." (PMID 33550277, 2021). "Downregulation of autophagy can be an effective anti-cancer approach because of the strong autophagy dependence of KRAS mutant cancer cells." (PMID 33925206, 2021). "When considering all cancer types, the number of base substitutions at the guanine in the first position of KRAS codon 12 is just 23% of the total number of substitutions across all codons." (PMID 34521464, 2021). "Growing evidence indicates that mutant KRAS reprograms intracellular fatty acid (FA) metabolism to regulate lipid storage and utilization and promote cancer metastasis and progression." (PMID 33801246, 2021). "Altogether these observations confirmed the ability of the oncogenic KRAS to promote an increased glycolysis in PDAC cancer cells." (PMID 33670598, 2021). "The HMOsisEC10 KRAS and HMOsisEC10 PIK3CA mutant cell lines in our study were insufficient, despite having driver mutations and aggressive behavior, to induce cancer development." (PMID 34202354, 2021). "The G12V is a well-known oncogenic mutation in KRAS (reported 10,797 times in COSMIC, the database of somatic mutations in cancers)." (PMID 34156985, 2021). "Previous reports have shown that oncogenic KRAS promotes cancer cell metabolism and proliferation by altering the AKT, MTOR, E2F, and MYC pathways." (PMID 34003553, 2021). "An allelic imbalance of KRAS and additional mutations in regulators and effectors of the MAP kinase pathway increase the signal strength that is associated with cancer progression." (PMID 34491463, 2021). "In the present study, a systematic analysis was performed to explore even further the possible therapeutic strategies in KRAS mutant cancer cells." (PMID 33925206, 2021). "A role of oncogenic KRAS in reprogramming cancer cell metabolism through activation of glucose metabolism has been documented in various cancer cell lines including pancreatic ones." (PMID 33436044, 2021).